BCL2 (BCL2 apoptosis regulator)
Diseases named in the same sentence as BCL2 in open-access papers (continued):
Sharing a sentence is not in itself a finding about the gene and the disease.
cancer (continued). "It has been clear for over a decade that the inhibition of apoptosis can contribute to the development for cancer, a finding first demonstrated in mice overexpressing both c-myc (driving the cell cycle) and Bcl-2 (which inhibits apoptosis) in the lymphatic system." (PMID 14647151, 2003). "In contrast, cortical adenomas and carcinomas showed heterogeneous Bcl-2 expression." (PMID 12085205, 2002). "The data suggest that overexpression of bcl-X-L results in an unusual phenotype with broad cross-resistance to non-MDR-related cytotoxins in vitro, and provide an interesting example of spontaneous overexpression of another member of the bcl-2 gene family in cancer." (PMID 9010037, 1997). "Of the 77 cancers, 37 (48% showed bcl-2 overexpression at diagnosis." (PMID 8883414, 1996). "Sixty-five per cent of the carcinomas contained bcl-2-positive cells." (PMID 7599047, 1995). "Expression of bcl-2 was investigated immunohistochemically in archival biopsies of normal (n = 8) and dysplastic bronchial epithelium (n = 56) and in 31 bronchial resection margins and their corresponding carcinomas." (PMID 7599047, 1995). "Additionally, the regulation of the PI3K/AKT/mTOR signaling pathway, reduction in the expression levels of Bcl-2, mTOR, and P70S6k, as well as the overexpression of pro-apoptotic proteins like Bax, demonstrate the multi-targeted mechanism of securinine in cancer therapy." (PMID 41001039, 2025). "Furthermore, MIA-690 sensitized cancer cells to IR-induced apoptosis by increasing annexin staining, caspase-3 activity, and Bax protein expression while downregulating the antiapoptotic protein Bcl-2." (PMID 40244089, 2025). "Moreover, resisting cell death is one of the iconic hallmarks of cancer reviewed by Hanahan and Weinberg, alternatively by up-regulating the expression of anti-apoptotic regulators such as BCL-2 and BCL-XL while down-regulating pro-apoptotic factors such as Bax, Bim, and Puma." (PMID 40799801, 2025). "For example, in humans, the decline in BCL2 expression and the alteration of the BCL2/BAX ratio with age has been associated with a decrease in tissue repair capacity and an increased incidence of age-related diseases such as cancer, cardiovascular disease, and neurodegenerative disorders." (PMID 40646808, 2025). "Furthermore, we found that cancer cells treated with pmiR-497@Nano might be induce the expression levels of apoptotic genes through significant downregulation of Bcl-2 level by fold change of 0.16 and 0.2 in HT29 and Caco2 cell lines, respectively." (PMID 39905036, 2025). "While in cancer cell lines Bcl-2 interacts with Bax/Bak, inhibiting apoptosis, Bax/Bak accumulation in the external mitochondrial membrane induced by cytotoxic conditions is inhibited when Bad is attached to Bcl-2 or co-activators from the BH3 family’s domains (Bid, Bim, PUMA, etc.)." (PMID 40076652, 2025). "Hence, while pomalidomide is described as pro-apoptotic through caspase-8 upregulation and inhibiting IAP-2 in cancer cell lines, in this study, we observed that pomalidomide treatment paradoxically supported cell survival through upregulating Bcl-2, improving the viability of CD4+ T cells." (PMID 39902962, 2025).
cancer (continued). "In cancer, PEDF can directly induce apoptosis in cancer cells by upregulating pro-apoptotic factors, primarily through the FAS/FASL pathway, while also downregulating antiapoptotic proteins like the B-cell lymphoma 2 (BCL2) family of proteins, which are associated with the intrinsic pathway." (PMID 39457573, 2024). "Our group recently demonstrated that the interaction of BCL2 and BAX through their TMDs contributes to the modulation of cell death; therefore, phenotyping mutations affecting these TMDs could have relevance for cancer cell survival." (PMID 38670940, 2024). "Our findings revealed an antagonistic interaction between cisplatin and high-THC cannabis extract, which could be linked to alterations in gene transcription associated with cell death (BCL2, BAD, caspase 10), DNA repair pathways (Rad52), and cancer pathways related to drug resistance." (PMID 38674023, 2024). "Consequently, the anti-apoptotic protein Bcl-2 is downregulated in cancer cells." (PMID 38169656, 2024). "Thus, the effects of BFC1108 are dependent on Bcl-2 expression in distinct cancer cells." (PMID 38329389, 2024). "Moreover, sesquiterpene lactones like helenalin found in A. lanata may disrupt Bcl2 function, promoting apoptotic cell death in cancer cells." (PMID 38738026, 2024). "Oleuropein induces apoptosis in several cancer cells via activation of an intrinsic mitochondrial pathway through upregulation of a pro-apoptotic Bax protein while the levels of antiapoptotic proteins such as BCL2 and survivin decrease leading to the activation of apoptosis machinery." (PMID 39203892, 2024). "Additionally, other cancer-related genes, including hTERT, c-kit, kRAS, and BCL2, have been identified as genes where G-quadruplex formation is involved in transcriptional regulation, and its stabilization by ligands attenuated promoter activity, ultimately inducing tumor apoptosis." (PMID 39407611, 2024). "In addition, the combination of luteolin and cisplatin not only significantly inhibited cell migration and invasion, but also promoted early apoptosis of cancer cells by down-regulating Bcl-2, and enhanced the anti-proliferative effect of cisplatin on ovarian cancer CAOV3/DDP cells." (PMID 39314630, 2024). "Moreover, studies also found that acacetin could induce a decrease of mitochondrial membrane potential in cancer cells, which is accompanied by the changes of protein levels of bcl-2, bax, and bak, and in turn induces apoptosis of cells." (PMID 38287075, 2024). "Moreover, the upregulation of the Bcl-2 gene has been observed in non-small cell lung cancer, providing a protective mechanism for cancer cells against apoptosis through the sequestration of pro-apoptotic family members and the modulation of IP3R-mediated calcium ion signaling." (PMID 39226162, 2024). "Furthermore, by examining the structural and functional effects of SNPs in Bcl-2, our finding may pinpoint novel targets for cancer therapy." (PMID 39840282, 2024). "However, the prognostic value of BCL-2 can vary across cancer types, as its expression may indicate resistance to certain chemotherapies, impacting treatment decisions." (PMID 39685591, 2024). "However, it also introduces a specific vulnerability to BCL2 inhibitors, which may be harnessed as a strategy in cancer therapy." (PMID 39605038, 2024). "It is well known that ROS plays a central role during cancer progression where it participates in all cellular events (cell survival, growth, differentiation, protein synthesis and inflammation), therefore Caspase 9, Caspase 3, Bax, BCL2 and TBARS expressions were assessed." (PMID 38286826, 2024).
cancer (continued). "Thus, Bcl-2 expression studies in various malignancies may help develop Bcl-2 inhibitor drugs as a novel therapy for cancer." (PMID 39252711, 2024). "Indeed, we discovered that 23-HBA decreased the phosphorylation level of STAT6 protein in M2 macrophages, accompanied by a decrease in M2-related cytokine IL-10 secretion and an inhibition of STAT3/Bcl-2 signaling of cancer cells, resulting in a reduction in 5-FU resistance." (PMID 38554148, 2024). "5-FU-miR-15a was also shown to significantly inhibit the expression of Yap1, Bcl2, Il6, and Mmp9, both alone and during treatment with TGFβ1 in murine and human Pancreatic Stellate Cells, suggesting the reduced proliferation and migration of pancreatic stellate and cancer cells." (PMID 38139352, 2023). "Furthermore, these stem cells produce exosomes bearing MiR-15a/MiR-16, which could negatively regulate cancer’s oncogenes BCL-2 for adjuvant therapy." (PMID 36683744, 2023). "In addition, AIFCM such as ganoderma lucidum polysaccharide, curcumin and artesunate could improve the sensitivity of cancer cells to radiotherapy by regulating apoptosis-related proteins including survivin, Bcl2, and Bax." (PMID 37497002, 2023). "Therefore, Bcl-2 has been identified as a target for cancer therapy." (PMID 37064948, 2023). "Inhibition of SAAL1 expression could regulate cancer growth via cyclin D1 and Bcl-2." (PMID 36973678, 2023). "Moreover, the prevalence of Bax and Bcl-2 as biomarkers was expected, as the pro-apoptotic protein Bax commits the cell to a mitochondrial suicide pathway and is considered one of the main targets of anti-cancer interventions." (PMID 36979499, 2023). "Therefore, Bcl-2 (as well as other Bcl-2 family members) has become an interesting target for drug development in combination with conventional chemotherapy to sensitize resistant cancer cells." (PMID 37760033, 2023). "Hence, this study is the first to demonstrate that GR inhibits the PM-induced COX-2/PGE2 pathway through mitochondrial ROS and that the Bcl-2/GR complex could be critical for inhibiting PM-mediated lung inflammation and cancer progression." (PMID 37919369, 2023). "Furthermore, this type of cancer was found to rarely occur in extra-thoracic organs as biologically distinct subsets, which often exhibit poorly differentiated histology and overexpress the well-known oncogenes BCL2 and KIT." (PMID 37179317, 2023). "Thus, targeting the Bcl‐2 proteins, especially the antiapoptotic proteins, may represent a promising approach for cancer treatment." (PMID 37970406, 2023). "In contrast to other papers examined in this study, the findings indicated that aconitine could promote the expression of apoptotic genes/proteins and excessive autophagy in cancer cells by upregulating Bax expression and downregulating Bcl-2 expression, ultimately leading to apoptosis." (PMID 37180714, 2023). "Therefore, one of the antitumor mechanisms that λ-COS-induced cytokines possess may rely on the downregulation of Bcl-2, making cancer cells more vulnerable to the enhanced immune system and chemotherapy." (PMID 37432179, 2023). "Furthermore, a recent study has demonstrated that increased miR-34c-5p expression in NPC cancer cells is associated with reduced cancer cell proliferation, metastasis, and epithelial-mesenchymal transition (EMT) and decreased BCl2/BAX ratio and β-CATENIN gene expression." (PMID 38116556, 2023).
cancer (continued). "The selection of the BCL2 gene was motivated by its significance as a crucial housekeeping gene and regulator of apoptosis in cancer cells and its critical role as a significant apoptosis inhibitor, often found in an overexpressed state across various cancer types." (PMID 38248163, 2023). "The increased ratio of Bax/Bcl-2 may enhance sensitivity of cancer radiotherapy." (PMID 37227584, 2023). "BCL2 and BAK1 genes are cell death regulators and sometimes irregular patterns of the expression of these genes could reveal some underlying issues, for example, cancer." (PMID 37576599, 2023). "Here, we performed a targeted sequencing panel of 324 cancer‐related genes (including ABL1, BCL2, CDH1, EGFR, etc.)at an average depth of 500× in all the specimens to identify mutations in genes that may be pivotal for synchronous primary cancer (BioProject accession number: PRJNA761143)." (PMID 36128740, 2022). "Specifically, 7‐Epitaxol increased Fas, TNF‐R1, DR5, DcR3 and DcR2 expressions, reduced Bcl‐2 and Bcl‐XL (anti‐apoptotic proteins) expressions, and increased Bid and Bim L/S (pre‐apoptotic proteins) expressions, leading to activation of caspase‐mediated cancer cell apoptosis." (PMID 36308422, 2022). "Since Disarib targets Bcl2, any cancer with a high Bcl2 level might benefit from Disarib treatment." (PMID 35885991, 2022). "In cancer cells, Nur77 functions in nucleus as a survival factor, but becomes a potent killer when certain death stimuli induce its migration to mitochondria, where it binds to Bcl-2 and conformationally converts it to a killer that triggers cyto c release and caspase activation." (PMID 36062172, 2022). "Therefore, a reduction in the number of Bcl-2-positive cells in the epithelium could imply cancer invasion from the epithelium to the lamina propria." (PMID 36013602, 2022). "Additionally, we evaluated the expression of some cancer‐related proteins in ex vivo tumors from both groups, including proliferation (Ki‐67 and Cyclin D1), anti‐apoptotic (BCL2), and stemness (NESTIN and SOX2) markers, collected at distinct time points according to animal survival times." (PMID 34919784, 2022). "Therefore, the level of Bcl‐2 has significant importance for ATO‐induced apoptosis in cancer cells." (PMID 34910369, 2022). "Further, low Bax/Bcl-2 ratios may result in poor prognosis and an increase in cancer invasion." (PMID 36013602, 2022). "In addition, the study had shown that BCL2 inhibitor ABT199 is generally considered to be effectively only for Bcl-2-dependent cancers, but when combined with cisplatin, it could inhibit TNBC cells viability with less side effects." (PMID 35414025, 2022). "Thus, the expression capacity of Bcl-2 of cancer cells may be recognized as one of the key indicators for cell growth after treatment with Ova." (PMID 35163851, 2022). "Therefore, they inhibit the prosurvival BCL-2 proteins, so cancerous cells may go through apoptosis and provide an alternative for cancer therapy." (PMID 35454775, 2022). "Thus, cancer mitochondria raise the cell death threshold by modulating the stress response pathway and survival-promoting factors, including members of the B-cell lymphoma 2 (BCL-2) family, to protect cancer cells from stress-induced death." (PMID 35269393, 2022). "Moreover, this study found that OIP5-AS1 was upregulated and could bind to miR-448 to upregulate the expression of Bcl-2, which in turn promoted cancer development." (PMID 35411833, 2022).
cancer (continued). "However, cancer cells upregulate anti-apoptotic proteins (e.g., Bcl-2 and Bcl-xL) or downregulate pro-apoptotic factors (e.g., Puma, Bax) to evade apoptosis, supporting their abnormal survival, therapeutic resistance and cancer recurrence." (PMID 35410300, 2022). "The success of these drugs has validated Bcl-2 as a therapeutic target for cancer, however further studies into overcoming the resistance to cell death afforded by the expression of anti-apoptotic proteins in cancer cells is needed to develop additional therapeutics." (PMID 36539401, 2022). "Therefore, Bcl-2 inhibition is a promising strategy for cancer treatment." (PMID 35123593, 2022). "Interestingly, numerous plant-based products have shown their role in activating cancer cell apoptosis through the BCL-2 pathway, for example, curcumin from Curcuma longa or graviola from Annona muricata, suggesting a great potential in the development of anticancer medicines." (PMID 36230771, 2022). "However, combining radiation for EGFR and Bcl-2 obstruction may be a new plan for targeting cancer stem cells." (PMID 35402265, 2022). "Since BCL-XL was suggested as a factor of resistance to direct BAX activation in our panel of cancer cell lines, we examined whether Navitoclax, a clinical BCL-XL/BCL-2 inhibitor, would be able to promote cytotoxicity against the same panel of cancer cell lines." (PMID 35256598, 2022). "The formed 99mtechnetium-coupled TFOs also bind to the TTS to form stable triplexes and inhibit bcl-2 gene transcription in vitro, indicating that TFOs are a promising carrier for gene-radiotherapy and may provide an additional therapeutic method for cancers with bcl-2 overexpression." (PMID 36618947, 2022). "The B-cell lymphoma 2 antiapoptotic protein, BCL-2, also plays an important role in the intrinsic apoptosis pathway and has been shown to contribute to chemoresistance in many cancers, implying that targeting BCL-2 could have a potential role in the treatment of TNBC." (PMID 36299882, 2022). "Interestingly, previous studies have reported that miR‐497 can suppress proliferation and induce apoptosis via the Bcl2‐related molecular axis in several tissues and cancers, including neuronal cells, the “human umbilical vein endothelial cells,” breast cancer, and multiple myeloma." (PMID 34994989, 2022). "In addition, PAB was evidenced to induce cell apoptosis in many cancer cells with significant increase in some proapoptotic protein expression (such as bax and cleaved-caspase-3) and significant reduction in some antiapoptotic protein expression (bcl-2)." (PMID 35747382, 2022). "Therefore, we can speculate that PPO may induce apoptosis of cancer cells by inhibiting the expression of BCL-2 protein and promoting the expression of Bax." (PMID 35268616, 2022). "Hence, cancer cells may develop resistance to apoptosis by changing the level of the Bcl2 and Bax protein expression." (PMID 36092142, 2022). "Given that cancer cell growth or apoptosis is influenced by the expression levels of anti‐apoptotic proteins, such as the family of Bcl‐2 and IAPs,31, 32 we next investigated whether dasatinib affects the expression levels of Bcl‐2, Mcl‐1 and XIAP in YD‐38 cells." (PMID 34318593, 2021). "Furthermore, lncRNA GHRLOS repressed Bcl-2 and upregulated Bax expression in cancer cell lines." (PMID 33968785, 2021). "Other series studies investigating ONC201 and ONC212 (imipridone) suggested that the upregulation of ISR could promote anti-cancer activity against solid and hematological malignancies, and help overcome the resistance to the B-cell lymphoma (BCL)-2 inhibitor venetoclax." (PMID 34944685, 2021).